INS (insulin)
Diseases named in the same sentence as INS in open-access papers (continued):
Sharing a sentence is not in itself a finding about the gene and the disease.
diabetes (continued). "The finding also suggests that patients with diabetes are at a high risk of renal decline might require insulin dosage adjustment on the basis of SCr scores and eGFR status." (PMID 36095019, 2022). "While it is true that T1DM is less common than T2DM, there are diagnostic ambiguities that can lead to people with diabetes or those on insulin being incorrectly diagnosed as having T1DM, making changes in the recurrence of characterized ESRD in T1DM less obvious." (PMID 35619856, 2022). "Pancreatic inflammation leads to structural and functional loss of islet cell mass leading to loss of insulin, glucagon, and pancreatic polypeptide, which leads to the development of difficult to control diabetes with large fluctuations in blood glucose, which are difficult to control." (PMID 35786076, 2022). "In conclusion, we estimated 12- to 60-month risks of PDAC in men and women at different stages of diabetes progression and found that risk is substantially higher in the diabetes populations than in the general population, especially in those with insulin initiation." (PMID 34728468, 2022). "The literature has identified an association between diabetes and an increased prevalence of psychiatric disorders such as depression or suicidality, particularly in those with a long history of diabetes and those on insulin therapy." (PMID 35943711, 2022). "Male sex, non-gallstone aetiology, and higher level of care were also significant risk factors for medication-treated diabetes and insulin-treated diabetes, with increasing age negatively associated with the development of insulin-dependent diabetes during follow-up." (PMID 36515672, 2022). "In the Diabetes Prevention Program, both decreased insulin sensitivity and insulin secretion were independently associated with the conversion to type 2 diabetes, but in other studies, the role of insulin secretion has remained unclear." (PMID 35050191, 2022). "For example, diabetes prevention and management recommendations, such as those based in the National Diabetes Prevention Program, typically encourage weight-loss via energy deficits to support insulin sensitivity and delay disease progression." (PMID 36221145, 2022). "Calorie restriction and exercise-mediated weight loss decreased mRNA levels of NLRP3 and IL-1β, and improved insulin sensitivity in diabetic subjects, demonstrating that pyroptosis contributes to the pathogenesis of IR and diabetes by mediating inflammation and β-cell destruction." (PMID 36009329, 2022). "Notably, these DMRs were enriched for proximity to significant genome-wide association study (GWAS) variants for BMI, height, body fat percentage, insulin sensitivity, insulinogenic index, diabetes and diabetes-associated cardiovascular disease." (PMID 36097183, 2022). "Besides, another common commensal microbe, A. muciniphila, a gram-positive bacterium, reduces insulin sensitivity and is inversely associated with the development of obesity and diabetes." (PMID 36219347, 2022). "SIRD was associated with PRSs for fasting insulin and diabetes." (PMID 35956377, 2022). "While MODY is classically characterized by early‐onset diabetes (<25 years), insulin independence and autosomal dominant inheritance, it is a genetically and clinically heterogeneous group of diabetes resulting from mutations in genes mostly involved in pancreatic beta cell function." (PMID 36208030, 2022). "A low level of potassium was associated with higher insulin levels and a higher risk of diabetes." (PMID 35411032, 2022). "ABCC8/KCNJ11 gain-of-function (GOF) mutations cause the permanent opening of the KATP channel, and thus reduce insulin secretion and eventually cause hyperglycemia with a wide spectrum of diabetes phenotypes, ranging from neonatal diabetes to MODY to adult-onset diabetes." (PMID 35052457, 2022).
diabetes (continued). "This insulin resistant state predisposes the individual to the development of metabolic syndrome and all its parameters such as dyslipidemia, fatty liver, arterial hypertension and type 2 diabetes mellitus later in life." (PMID 36440208, 2022). "Impaired fasting glucose (IFG) and impaired glucose tolerance (IGT) are high-risk factors of diabetes development and may be caused by defective insulin secretion in pancreatic beta-cells." (PMID 35453520, 2022). "Xbp1 deletion may therefore result in impaired compensatory insulin secretion under conditions of obesity, causing diabetes." (PMID 35316840, 2022). "Among the eating disorders associated with diabetes, anorexia is a rare condition that hampers patient management and increases the incidence of life-threatening complications due to insulin treatment restriction, prolonged fasting and compensatory behaviors (such as the induction of vomiting)." (PMID 36142725, 2022). "However, it is true that they agreed that chronic heavy drinking causes a disruption in glucose homeostasis, increases insulin resistance, and thus the risk of diabetes." (PMID 35565924, 2022). "Indeed, targeting classical inflammatory molecules including IL-1, IL-6 and TNF have been shown to reduce the risk of diabetes and improve insulin sensitivity in some studies, although with variable effects." (PMID 35480482, 2022). "Currently, the mechanism by which KATP variants induce high diabetes risk remains unclear, possibly involving inadequate insulin secretion, resistance to insulin, or (and) impaired glucagon secretion." (PMID 35402560, 2022). "At an ICER of £20,000, the maximum justifiable cost was estimated to be £105 for individuals with a high BMI, £159 for individuals with a high BMI and a high HbA1c (high risk of diabetes) and £88 for individuals with a diagnosis of type 2 diabetes on a single non-insulin medication." (PMID 35151300, 2022). "It seems that not only Mg serum concentration and its intake with diet can modify the risk of diabetes and metabolic disorders but also the supplementation of this micronutrient may affect the glucose and insulin levels." (PMID 35565682, 2022). "This increased confidence in the management of insulin, including comfort with a basal/bolus regimen, is foundational to the intensive insulin therapy which is associated with improvements in short- and long-term diabetes health outcomes." (PMID 36589850, 2022). "Obesity, diabetes mellitus, hypertension, and cardiovascular disease are believed to be among the underlying conditions that give rise to the low‐grade inflammation that impairs insulin signaling." (PMID 35088922, 2022). "Diabetes mellitus, one of the most common metabolic conditions causing hyperglycemia due to disruption in the metabolism of carbohydrates, proteins, and lipids induced by a relative or absolute decline in insulin secretion and insulin action." (PMID 35078449, 2022). "The functional enrichment analysis of the DEGs showed clustering around the genes CXCL5, EGF, and SPARC, which are associated with diabetes, obesity, and insulin secretion and enriched in disease ontology terms of metabolic disease, diabetes, and glucose metabolism disease." (PMID 36138412, 2022). "Alteration in carbohydrate metabolism may cause serious health problems such as diabetes and obesity, where a decline in function or secretion of insulin leads to an increase in blood glucose level and hence the ultimate onset of diabetes mellitus." (PMID 36235206, 2022). "In addition, the intake of high-viscosity foods can help reduce both blood glucose levels and insulin response after meals, thereby reducing the risk of diabetes." (PMID 37431003, 2022). "Diabetes mellitus caused by a deficiency in insulin secretion or function, or both, and results in tissue and vascular damage, as well as a variation of complications.Type 2 diabetes (T2D) is a chronic disorder of food metabolism induced by decreased insulin action." (PMID 36518143, 2022).
diabetes (continued). "Adherence to any of the Medi, DASH, and MIND dietary patterns could improve insulin sensitivity, and reduce the likelihood of diabetes and inflammation, in turn reducing the risk of dementia and AD." (PMID 36458172, 2022). "The impaired insulin pathway causes diabetes, which is closely related to AD." (PMID 36437990, 2022). "However, associations between diabetes status and nutritional condition and use of some medications (insulin/steroids) are complex and can lead to poor glycemic control through increased insulin resistance and reduced β-cell secretory function." (PMID 34761326, 2022). "Illegitimate internet pharmacies, with rogue internet pharmacies being the worst offenders, allow patients to access Humalog and NovoLog insulin with minimal information, predisposing these patients to poor diabetes control and potential development of adverse events." (PMID 35156937, 2022). "However, any shortage in insulin hormone or elevated insulin insensitivity causes an imbalance in the metabolic process, which can cause a life-threatening disorder known as “diabetes mellitus”." (PMID 35723344, 2022). "Among many anti-diabetes medications, metformin (the first-line oral medication for diabetes) may decrease the risk of gastric cancer, while insulin might increase this risk." (PMID 35027671, 2022). "Because the difference in body weight was attenuated after excluding measurements after the diagnosis of diabetes, the difference might result from progressive insulin deficiency and anabolic effect of insulin or loss of energy due to glucosuria (or both)." (PMID 34951657, 2022). "Observational data have shown that use of insulin is associated with an adverse prognosis in people with heart failure and diabetes, and that higher HbA1c is a risk factor for developing heart failure in people with diabetes." (PMID 35717169, 2022). "Vitamin D deficiency might increase neurodegenerative risk, in part through ted development of IR and diabetes by reducing insulin signaling." (PMID 36458172, 2022). "Intensive insulin therapy was first linked to retinopathy in the 1980s in T1 diabetes patients." (PMID 35227220, 2022). "Of note, in the models for assessing the association between insulin AUC or insulin resistance indices and cancer risk, a steady significant association between the progression to diabetes and cancer risk existed simultaneously (HR ranged from 1.87 (P = 0.001) to 2.30 (P < 0.0001)." (PMID 35256755, 2022). "Since obesity is a high-risk factor for diabetes, we tested whether exercise could improve insulin sensitivity in obese mice." (PMID 36615677, 2022). "The dysfunction of β-cells, which occupy most Langerhans islets in the pancreas, is one of the causes of insulin secretion failure, and research related to the analysis of insulin secretory function of pancreatic β-cells has contributed to the development of diabetes medicine." (PMID 36292936, 2022). "INS mutations identified in Vietnamese patients with neonatal diabetes mellitus." (PMID 35518939, 2022). "The CDKAL1 genetic variants could predict the development of diabetes in individuals with impaired insulin secretion, which indicates that there may be potential synergistic and interactive effects among different risk factors." (PMID 36183068, 2022). "Diabetes mellitus (DM) is a metabolic disease caused by a combination of genetic, environmental factors and dietary habits and is characterized by chronic elevation of blood glucose and inadequate insulin secretion." (PMID 36339149, 2022). "Intensive studies have revealed that there is a variety of abnormal expression patterns of lncRNAs in various tissues under insulin-resistant status, and dysregulated lncRNA profiles are associated with metabolic diseases including diabetes and nonalcoholic steatohepatitis (NASH)." (PMID 36555704, 2022). "LncRNAs are implicated in the pathophysiology of insulin resistant states such as diabetes." (PMID 36057662, 2022).
diabetes (continued). "Sustained endogenous insulin and C-peptide secretion is associated with reduced diabetes related complications, but underlying mechanisms remain unclear." (PMID 35222269, 2022). "Diabetes with onset from 6 months to early adulthood is classified as type I diabetes and is characterized by immune-mediated destruction of pancreatic beta cells, resulting in absolute insulin-deficient diabetes." (PMID 35966750, 2022). "Low levels may reduce insulin secretion and insulin sensitivity, whereas the risk of diabetes decreaseswith higher dosages." (PMID 35892446, 2022). "In summary, combined evidence from the COVID-19 model connects key players both directly and synergistically to defective insulin secretion and insulin resistance in target organs, providing a rationale for both diabetes as risk factor and a consequence of COVID-19." (PMID 39086962, 2022). "Diabetes mellitus is characterized by hyperglycemia caused by decreasing insulin secretion or insulin resistance, and 592 million people will have diabetes mellitus by the year 2035 worldwide according to the International Diabetes Mellitus Federation prediction." (PMID 36140990, 2022). "Diabetes, known as a metabolic disorder, is the insensitivity or deficiency of insulin." (PMID 35101010, 2022). "However, prolonged exposure of pancreatic β-cells with high glucose or high fat leads to a decrease in insulin production by β-cell and causes diabetes." (PMID 36060809, 2022). "Additionally, the lack of tonic suppression of insulin secretion by leptin, leads to increased insulin production by pancreatic beta cells, which then results in pancreatic beta cell dysfunction – a major cause of type 2 diabetes mellitus." (PMID 36381191, 2022). "Diabetes and impaired insulin signaling in the brain are linked to the pathogenesis of AD." (PMID 36148311, 2022). "In addition to interpreting CGM data and discussing associated insulin dose changes, we also discussed the burden of alarms, skin irritation, and the psychosocial considerations of starting and maintaining diabetes technology use." (PMID 36589850, 2022). "Type 1 diabetes mellitus is dependent on insulin therapy, but this treatment may cause severe hypoglycemia." (PMID 35761839, 2022). "Diabetes mellitus (DM) is a metabolic disease caused by a disorder in insulin secretion." (PMID 36296499, 2022). "Our study showed that long-term administration of Po.Cr reduces the hyperlipidemia associated with diabetes, which suggests the presence of phenols and flavonoids that might enhance insulin release from pancreatic β-cells, as well as decrease LDL oxidation." (PMID 36588726, 2022). "This study suggests that VDS may improve TC, TG, and insulin concentration in the elderly, especially in short-term intervention duration and in patients with vitamin D deficiency and diabetes." (PMID 35752843, 2022). "Diabetes mellitus is often associated with accelerated gastric emptying; subjects with 1DM were treated with pramlintide prior to a meal, along with their usual dose of insulin." (PMID 35456307, 2022). "Furthermore, an enzyme with ferulic acid esterase activity isolated from Lactobacillus johnsonii showed a potential effect on diabetes via stimulation of insulin production by ferulic acid and alleviation of symptoms caused by diabetes." (PMID 36112580, 2022). "Therefore, the deficiency of insulin and/or the ineffectiveness of the insulin produced are the main causes that disturb the metabolic process in diabetes; this results in the sugar present in the blood." (PMID 35478694, 2022). "This behavior may also alter the pathogenesis of early steps in insulin action, such as signal transduction and glucose transport, increasing the risk of micro-and macrovascular complications in patients with diabetes mellitus." (PMID 35160077, 2022).
diabetes (continued). "For SDS intake in the gastrointestinal tract, a slow glucose release property accompanied by a low insulin level was observed, which might provide wide health benefits to reduce the risk of diabetes or metabolic syndrome." (PMID 36613304, 2022). "STZ also causes diabetes by damaging beta-cells of the Islets of Langerhans in the pancreas due to uncontrolled production of reactive oxygen species (ROS) leads to decrease in insulin synthesis and release." (PMID 35620596, 2022). "In a large, multiethnic population of a Dallas Heart Study including 6586 study participants, plasma Gal-3 was associated with diabetes prevalence and the incident diabetes mellitus, possibly through the inflammatory pathway contributing to impaired insulin secretion and β-cell fibrosis." (PMID 35327386, 2022). "Also, early identification of children with risk factors associated with adherence to insulin pump therapy allows for improving diabetes management." (PMID 36422210, 2022). "Diabetes can be classified according to its cause into type 1 diabetes (insufficient insulin production, common in children and adolescents) and type 2 diabetes (T2D; insulin resistance, common in obese adults), with over 95% of people with diabetes experiencing T2D." (PMID 36157443, 2022). "However, it was associated with the expression of miRNAs correlated with type 1 diabetes mellitus, with a particular significant overexpression of hsa-miR-29a-3p implicated in insulin production and secretion." (PMID 36140215, 2022). "On the other hand, TNF-α is a cytokine largely expressed in adipose tissue in diabetes mellitus, which may be associated with impaired insulin sensitivity in GDM." (PMID 35390031, 2022). "In addition, mitochondrial dysfunction has been associated with insulin-secreting pancreatic β-cell loss in triggering diabetes and vascular endothelial damage due to the accumulation of redox-sensitive gelatin matrix metalloproteinases in DR." (PMID 36362154, 2022). "Zhao scholars suggested that the higher risk of diabetes in the high PBF group among those with normal BMI may be related to their low insulin sensitivity index." (PMID 36387861, 2022). "It has been suggested that low alcohol intake can improve insulin sensitivity, and thus might indirectly influence the risk of MM via diabetes‐ or obesity‐linked mechanisms." (PMID 35846225, 2022). "Multiple logistic regression analyses revealed that only a longer duration of diabetes (p=0.001) and receiving insulin therapy alone (p=0.004) or a combination of oral anti-diabetics with insulin (p<0.001) were significantly associated with inadequate glycemic control." (PMID 35891859, 2022). "This scenario is similar to the dyslipidemia associated with diabetes and insulin-resistant states, where an increased generation of IDL, small and dense LDL particles, and triglyceride-enriched HDL particles is observed, and which has been related to an increased atherogenic risk." (PMID 35625770, 2022). "The increased risk of diabetes may also be associated with insulin resistance, reduced insulin sensitivity, and abnormal blood glucose regulation, which is thought to be mediated by muscarinic M3 receptor antagonism." (PMID 35280179, 2022). "A previous study in India also demonstrated that ingestion of excessive dairy could reduce the insulin sensitivity of individuals, thereby affecting the risk of diabetes." (PMID 36225884, 2022). "Normal HbA1C values confirm the exclusion of manifest diabetes in overweight and obese participants who are at risk for T2D but in whom elevated insulin release may still compensate for reduced insulin sensitivity (mean HOMA-2: 2.2 ± 0.08, range 1.2–3.5)." (PMID 36170006, 2022). "Clinical characteristics of probands at diagnosis of diabetes resulting from an INS gene mutation." (PMID 35518939, 2022). "CKD can cause alterations in glucose and insulin metabolism in patients with diabetes." (PMID 35908248, 2022).